FGF21 (fibroblast growth factor 21)
Diseases named in the same sentence as FGF21 in open-access papers (continued):
Sharing a sentence is not in itself a finding about the gene and the disease.
rectal cancer (5 papers, 2021 to 2024). A primary or metastatic malignant neoplasm that affects the rectum. "For instance, one study by Harlid and colleagues, examined ~160 proteins and other biomarkers and found that fibroblast growth factor 21 and pancreatic prohormone were associated with risk of colon and rectal cancer, respectively." (PMID 35805033, 2022). "In the subgroup analyses based on tumor site, FGF-21 (OR: 1.23, 95% CI 1.03–1.47) and 5’NT (OR: 0.86, 95% CI 0.79–0.99), were associated with colon but not rectal cancer, whereas PPY (OR: 1.47, 95% CI 1.12–1.92) was associated with rectal but not colon cancer." (PMID 33664295, 2021). "However, exploratory subgroup analyses showed associations between FGF-21 and colon cancer risk (multivariable OR per 1 SD: 1.23 95% CI 1.03–1.47) as well as between PPY and rectal cancer risk (multivariable OR per 1 SD: 1.47 95% CI 1.12–1.92)." (PMID 33664295, 2021). "Similarly, Harlid and colleagues have identified that fibroblast growth factor 21 (FGF-21) and pancreatic prohormone (PPY) are associated with the risk of colon and rectal cancers, respectively, in plasma samples from asymptomatic patients and in a pre-diagnostic setting." (PMID 38396959, 2024). "(2021) showed that fibroblast growth factor 21 (FGF21) was associated with early, but not late stages of colon cancer, while pancreatic prohormone (PPY) was a promising biomarker for rectal cancer detection." (PMID 37228491, 2023). "However, neither FGF21 nor PPY could be used as stand-alone biomarkers for colon or rectal cancer but might be used as an efficient tool to discriminate between different subtypes of CRC." (PMID 37228491, 2023).
renal dysfunction (5 papers, 2013 to 2023). "In our study, we did not obtain any association between the values of creatinine clearance and FGF21 levels, suggesting that the elevated serum FGF21 levels were not due to a renal dysfunction." (PMID 27358750, 2016). "The effects on lipid parameters, fibrinogen, and FGF21 were investigated in patients receiving statins, with analysis stratified by the presence or absence of renal dysfunction." (PMID 31698825, 2019).
systemic inflammatory response syndrome (5 papers, 2013 to 2024). SIRS is a serious condition related to systemic inflammation, organ dysfunction, and organ failure. "Noteworthy, other researchers demonstrated a correlation between FGF21 level and CRP level in patients with systemic inflammatory response syndrome and had even proposed FGF21 as a non-specific marker for systemic inflammation." (PMID 38983722, 2024).
thyroid cancer (5 papers, 2019 to 2025). "Previous works reported an elevated serum level of FGF21 in aggressive thyroid cancer yet cannot precisely determine the origin of this upregulation of FGF21." (PMID 34572066, 2021). "Although our results suggested that metabolic dysregulation increased serum FGF21 levels, we were unable to precisely determine the origin of FGF21 in thyroid cancer patients." (PMID 31408968, 2019). "Our study revealed that FGFR signaling was upregulated in thyroid cancer in response to increased serum levels of FGF21 due to metabolic stress." (PMID 31408968, 2019). "Our findings demonstrated the role of serum FGF21 as a predictive biomarker for tumor aggressiveness in thyroid cancer." (PMID 31408968, 2019). "Taken together, FGF21 promoted migration and invasion of thyroid cancer cells by upregulating FGFR signaling." (PMID 31408968, 2019). "We only measured serum levels of FGF21 in patients with thyroid cancer at the time of initial diagnosis." (PMID 31408968, 2019). "Our study demonstrated that upregulation of FGF21 due to metabolic stress had an important role in tumor progression in thyroid cancer." (PMID 31408968, 2019). "We examined expression levels of FGF21, FGFRs, and KLB in human thyroid tissue and the FGF21–FGFR signaling axis in thyroid cancer cells treated with recombinant FGF21 (rFGF21)." (PMID 31408968, 2019). "To determine the effect of FGF21 on tumor aggressiveness in thyroid cancer, we evaluated the expression levels of FGFRs, such as FGFRs and KLB, and phospho-FGFR in normal thyroids and thyroid cancer cell lines." (PMID 31408968, 2019). "In conclusion, FGF21 had a novel effect on tumor progression through upregulation of the EMT signaling axis in differentiated thyroid cancer." (PMID 31408968, 2019). "To determine the mechanism responsible for the promotion of aggressiveness of thyroid cancer cells by FGF21, we analyzed the downstream targets of FGFR pathways." (PMID 31408968, 2019). "We demonstrated a novel effect of FGF21 in the regulation of tumor aggressiveness in thyroid cancer." (PMID 31408968, 2019). "We focused on the endocrine effects of FGF21 in the tumorigenesis of differentiated thyroid carcinomas using PTC cell lines (TPC-1 and BCPAP) treated with rFGF21." (PMID 31408968, 2019). "A recent study revealed that FGF21 mediates invasion and metabolic disorders in thyroid cancer and that elevated serum FGF21 levels in patients with thyroid cancer may be a marker of tumor progression." (PMID 33753729, 2021). "Thus, in the present report, we investigated the serum levels of FGF21 in patients with thyroid cancer, and examined various metabolic parameters in patients categorized into high and low FGF21 groups." (PMID 31408968, 2019). "Previously, we described a reduction of oxidative phosphorylation in patients with thyroid cancer harboring the BRAF mutation, and we hypothesized that FGF21 was induced in the thyroid due to mitochondrial stress associated with thyroid tumorigenesis." (PMID 31408968, 2019). "This study investigated whether FGF21 has a role in regulating tumor aggressiveness in thyroid cancer." (PMID 31408968, 2019). "Higher serum levels of FGF21 were found in patients with thyroid cancer than in control participants, and were significantly associated with body mass index (BMI), fasting glucose levels, triglyceride levels, tumor stage, lymphovascular invasion, and recurrence." (PMID 31408968, 2019). "However, thyroid cancer cells treated with doxycycline, an inducer of mitochondrial stress, did not induce FGF21 expression." (PMID 31408968, 2019).
age-related macular degeneration (4 papers, 2021 to 2024). Age-related loss of vision in the central portion of the retina (macula), secondary to retinal degeneration. "FGF21 administration decreased neovascular lesions in two models of neovascular age-related macular degeneration has been observed recently." (PMID 35004861, 2021). "Moreover, FGF21 administration attenuated the hyperactivity of the intraocular complement system, thereby ameliorating the occurrence and development of age-related macular degeneration." (PMID 38789571, 2024).
anemia (4 papers, 2019 to 2024). A reduction in the number of red blood cells, the amount of hemoglobin, and/or the volume of packed red blood cells. "Our study is the first to show the increase of FGF21 in pediatric patients with anemia, supporting the presence of mitochondrial dysfunction in an anemic pediatric population where iron deficiency anemia is the majority." (PMID 39124668, 2024). "In our study, for children mostly with iron deficiency anemia, we found that FGF21 (with a cut-off level of ≥0.745 pg/mL) and NOS (with a cut-off grade of ≥1.265 μg/mL) levels increased compared to non-anemic children." (PMID 39124668, 2024). "Child onset anemia is an area of investigation concerned with the association of serum eNOS and FGF21 elevation." (PMID 39124668, 2024). "Our research demonstrates that anemia is linked to mitochondrial dysfunction, as indicated by elevated levels of FGF21 and eNOS." (PMID 39124668, 2024). "In cord blood, moderate to severe anemia at any time point in pregnancy was associated with higher levels of FGF-21, whereas malaria exposure in the third trimester was associated with lower FGF-21 levels in cord blood." (PMID 37795192, 2023). "A significant cut-off point of ≥0.745 pg/mL for FGF21 was found to predict anemia (AUC = 0.690; p = 0.008) with a sensitivity of 88.24% and specificity of 53.12%." (PMID 39124668, 2024). "The study aims to determine the discriminatory thresholds, specificity, and sensitivity of the novel biomarkers FGF21, GDF15, and NOS in diagnosing mitochondrial dysfunction associated with pediatric anemia." (PMID 39124668, 2024). "A cut-off point of ≥0.745 pg/mL for FGF21 was found to predict anemia (AUC = 0.690; p = 0.008) with a sensitivity of 88.24% and specificity of 53.12%." (PMID 39124668, 2024). "The findings of our research reveal the correlation between anemia-related elevation in FGF21 and NOS levels and the potential development of mitochondrial dysfunction." (PMID 39124668, 2024). "This study aims to explore the correlation between pediatric anemia and mitochondrial markers, specifically fibroblast growth factor 21 (FGF21), growth/differentiation factor 15 (GDF-15), and nitric oxide synthase (eNOS)." (PMID 39124668, 2024). "The study revealed that FGF21 levels ≥ 0.745 pg/mL and eNOS levels ≥ 1.265 μg/mL predicted anemia." (PMID 39124668, 2024). "Notable associations with morphotic blood elements highlights the unknown relationship of FGF21 with anemia or other hematological disturbances in psoriasis." (PMID 31847236, 2019). "A significant gap exists in the current literature regarding the association between mitochondrial dysfunction and anemia in a dominant pediatric population with iron deficiency anemia, as evidenced by the absence of studies utilizing the markers of FGF21, GDF-15, and NOS." (PMID 39124668, 2024). "In our analysis, we observed elevated levels of FGF21 (≥0.745 pg/mL) and NOS (≥1.265 μg/mL) in children primarily diagnosed with iron deficiency anemia as compared to non-anemic children." (PMID 39124668, 2024). "The change in serum FGF21 and GDF-15 in anemia or iron deficiency anemia is not reported." (PMID 39124668, 2024).
arteriosclerosis (4 papers, 2015 to 2022). A vascular disorder characterized by thickening and hardening of the walls of the arteries. "Based on these results, FGF21 has been proposed to be associated with arteriosclerosis." (PMID 26223891, 2015). "However, the role of FGF21 in arteriosclerosis remains unclear." (PMID 26223891, 2015).
brain infarction (4 papers, 2016 to 2025). Tissue necrosis in any area of the brain, including the cerebral hemispheres, the cerebellum, and the brain stem. "MRI and neurobehavioral assessments of wild-type (WT) and FGF21−/− tMCAO model mice revealed a deteriorated consequence of the loss of FGF21, with exacerbated brain infarction and neurological deficits." (PMID 40021824, 2025). "To evaluate the role of FGF21 in ischemic brain injury, we subjected FGF21−/− and wild-type (WT) mice to focal cerebral ischemia and assessed the size of the brain infarction via triphenyltetrazolium chloride (TTC) staining and HE staining." (PMID 40021824, 2025). "After FGF21 administration, the size of the cerebral infarction decreased in both groups." (PMID 35096806, 2021).
complication (4 papers, 2015 to 2024). Any disease or disorder that occurs during the course of, or because of, another disease, treatment, or procedure. "Increased levels of FGF-21 were potentially correlated with a decreased likelihood of developing neurological complications in T2D patients, and hGDNF elevated the risk of T2D with peripheral vascular complications." (PMID 38606083, 2024). "Existing evidences have proved the strong protective effects of FGF21 on diabetic cardiovascular complications, such as inhibition of fibrosis and anti-oxidative stress, as well as reduction of apoptosis and inflammation levels in different diabetic cardiovascular complications models." (PMID 34349728, 2021). "Several evidences demonstrated that histone methylation of the Fgf21 promoter may involve in the development of diabetic vascular complications." (PMID 34349728, 2021). "FGF21 deletion-aggravated DCM indicates that FGF21 may be a therapeutic target for the treatment of diabetic cardiovascular complications." (PMID 25823710, 2015).
diabetic neuropathy (4 papers, 2022 to 2024). A chronic, pathological complication associated with diabetes mellitus, where nerve damages are incurred due to diabetic microvascular injury involving small blood vessels that supply these nerves, resulting in peripheral and/or autonomic nerve dysfunction. "This study seeks to delve into the potential of diosmin and hesperidin in promoting nerve regeneration in a diabetic neuropathy rat model while also examining their influence on FGF21 and gal3 levels." (PMID 39459367, 2024). "Recently, researchers have shown that FGF21 has regenerative capability in the PNS by suppressing oxidative stress, and the FGF21 levels were elevated in patients with diabetic neuropathy after aerobic training." (PMID 39156689, 2024). "Background and Objectives: This study aimed to investigate the protective effect of diosmin and hesperidin in diabetic neuropathy using a rat model, focusing on their impact on nerve regeneration through the fibroblast growth factor 21 (FGF21) and galectin-3 (gal3) pathway." (PMID 39459367, 2024). "In addition, FGF21 also has a certain therapeutic effect on diabetic neuropathy by reducing neuroinflammation and oxidative stress, and enhancing the protection of neuronal mitochondria, thereby alleviating diabetic neurodegeneration." (PMID 39296716, 2024). "However, the effects of increased FGF21 and irisin production onvarious adipokines and inflammatory markers as a result of physical activity havenot been studied in diabetic neuropathy." (PMID 39077619, 2022). "We concluded that monitoring of FGF21 levels may predict theefficacy of aerobic exercise in diabetic neuropathy, but other lifestyle factorssuch as changes in eating habits or lifestyle-oriented motivations might alsohave contributed." (PMID 39077619, 2022). "In addition, wefirstly analyzed the change in FGF21 levels in diabetic neuropathy and found asignificant increase after training program." (PMID 39077619, 2022). "Monitoring of FGF21 levels may predict the efficacy of aerobicexercise in diabetic neuropathy." (PMID 39077619, 2022). "However,there are no previous data in the literature on whether physical activitydirectly or indirectly elevates FGF21 in patients with diabetic neuropathy.Therefore, further studies are necessary to validate our results." (PMID 39077619, 2022). "The observed reduction in perineural thickness, elevation of plasma FGF21 levels, and reduction in gal3 and MDA levels collectively suggest that diosmin and hesperidin could be valuable agents in mitigating the underlying pathophysiology of diabetic neuropathy." (PMID 39459367, 2024).
diastolic heart failure (4 papers, 2016 to 2022). Heart failure caused by abnormal myocardial relaxation during diastole leading to defective cardiac filling. "Literatures review showed a higher FGF21 in patient with diastolic heart failure or CAD with greater risk of MACEs but have a cardio protecting and antiarrhythmic effect in animal studies." (PMID 36180826, 2022). "In conclusion, this study showed that circulating FGF21 is associated with diastolic dysfunction and 1-year adverse events in patients with diastolic heart failure." (PMID 27650781, 2016). "As such, we designed this study to investigate the role of circulating FGF21 in diastolic heart failure, and compare the predictive performance of FGF21 with N-terminal Pro-Brain Natriuretic Peptide (NT-pro-BNP)." (PMID 27650781, 2016). "In addition, compared with NT-pro-BNP, circulating FGF21 can better predict the presence of diastolic dysfunction and adverse cardiac events in diastolic heart failure patients within 1 year." (PMID 35069790, 2022). "The aim of this study was to investigate the impact of FGF21 in diastolic heart failure." (PMID 27650781, 2016). "Moreover, circulating FGF21 was non-inferior to NT-pro-BNP in predicting the presence of diastolic dysfunction, as well as predicting 1-year adverse cardiac events in patients with diastolic heart failure." (PMID 27650781, 2016).
dilated cardiomyopathy (4 papers, 2018 to 2023). Cardiomyopathy which is characterized by dilation and contractile dysfunction of the left and right ventricles. "Despite this, the association of FGF21 levels with poor prognosis in dilated cardiomyopathy patients remained significant after adjusting for AF." (PMID 36028609, 2023).
epilepsy (4 papers, 2020 to 2022). A brain disorder characterized by episodes of abnormally increased neuronal discharge resulting in transient episodes of sensory or motor neurological dysfunction, or psychic dysfunction. "Nineteen patients had serum FGF21 levels above the upper limit (116.591 pg/ml), including 10 patients with epilepsy (7/15, 46.7%), 5 patients with myasthenia gravis (5/6, 83.3%), 3 patients with DMD (3/7, 42.9%), and 1 patient with viral encephalitis (1/2, 50%)." (PMID 35498801, 2022). "At her second and third admission with epilepsy, a relatively mild rise in FGF‐21 was seen." (PMID 32071844, 2020). "The results revealed that serum FGF21 and GDF15 levels were variably increased in the NMD group, especially in the patients with DMD and epilepsy." (PMID 35498801, 2022).
hypogonadism (4 papers, 2019 to 2025). A disorder characterized by decreased function of the gonads. "Taken together, these data highlight FGF21 as a plausible hormonal link between male obesity and hypogonadism that merits further investigation." (PMID 39885510, 2025). "Furthermore, integrated multi-OMICs analysis identified high FGF21 and low cortisol levels as novel predictors of metabolic dysfunction in obese individuals beyond the effect of hypogonadism." (PMID 39885510, 2025).